MMP13 (matrix metallopeptidase 13)
Diseases named in the same sentence as MMP13 in open-access papers (continued):
Sharing a sentence is not in itself a finding about the gene and the disease.
colorectal cancer (32 papers, 2004 to 2025). A primary or metastatic malignant neoplasm that affects the colon or rectum. "Increased expression of MMP13 has also been associated with poor prognosis in patients with colorectal cancer metastasis to the liver." (PMID 40839695, 2025). "MMP-3 and MMP-13 is upregulated in human colorectal carcinomas, and MMP-13 activity is associated with poor prognosis in colorectal cancer." (PMID 28505114, 2017). "Some previous studies showed that MMP13 is abnormally expressed in some solid tumors, such as papillary thyroid carcinoma and colorectal cancer and is associated with progression and metastasis." (PMID 27227769, 2016). "This is a clear indication that MMP-2 is a key factor in the regulation of cell migration, however it should not be ruled out that other ECM degrading MMPs such as MMP-1, MMP-7, MMP-9 and MMP-13 have been shown be associated with Colorectal cancer progression." (PMID 24130681, 2013). "MMP13 has previously been associated with fibrotic liver disease and its expression in tumors has been associated with poor prognosis in patients with colorectal cancer metastasis to the liver." (PMID 25880591, 2015). "In addition, increased expression of MMP13 has been associated with poor prognosis in patients with colorectal cancer metastasis to the liver." (PMID 25880591, 2015). "There is evidence that the upregulation of NOX4, CXCL8, CXCL5, GDF15, and MMP13 genes in colorectal cancer promotes the metastasis of cancer cells, so a sustained upregulation of these genes after aspirin treatment will not benefit from treatment." (PMID 41425852, 2025). "Based on a molecular docking method, it also inhibits post-translational forms of MMP-8 and MMP-13 in colorectal cancer progression and significantly palliates colorectal cancer invasion and metastasis." (PMID 38611849, 2024). "MMP-13 expression was assessed in 137 biopsy samples from 105 patients with colorectal adenomas and colorectal cancer." (PMID 27716617, 2016). "Studies indicate that expression of MMP-13 is closely related to the development and progression of colorectal cancer." (PMID 27716617, 2016). "In high grade adenomas and colorectal cancer MMP-13 was located with a moderate and strong staining." (PMID 27716617, 2016). "The expression of MMP-13 seems to be closely related to development, invasion, and progression of colorectal cancer." (PMID 27716617, 2016). "Immunohistochemical analysis of murine experimental MC38 colon carcinoma tumors in the liver and human colorectal cancer metastases to the liver show MMP13 staining within these tumors." (PMID 25880591, 2015). "Overexpression of MMP-13 has been reported for head and neck squamous carcinomas (HNSCCs), esophageal, gastric and colorectal cancers and skin cancers." (PMID 26193700, 2015). "MMP13 immunoreactivity in the cytoplasm of tumor cells has also been identified in 91% of 249 colorectal cancers resections." (PMID 22253746, 2012). "In this context, MMP-13 has been shown to play a role in tumor progression of other gastrointestinal tumor entities such as colorectal carcinoma, and hepatocellular carcinoma." (PMID 20946664, 2010). "In previous studies, we investigated the roles of MMPs including MMP2, MMP7, MMP8, MMP9 and MMP13 in the mice colorectal cancer model tissue, and observed that MMP7, MMP8, MMP9 are more important in colorectal cancer invasion and migration, and that MMP7 is regulated by NF-κB pathway." (PMID 31299935, 2019). "CCR4-mediated MMP13 activity in colorectal cancer cells requires NF-κB." (PMID 30140381, 2018). "Furthermore, we recapitulated the gene expression levels of Mmp3, Mmp10, and Mmp13 from large cohorts of ulcerative colitis (UC) and colorectal cancer (CRC) patients that are available from the GEO database (GSE38713 and GSE37364)." (PMID 25742789, 2015).
colorectal cancer (continued). "Besides, literature reports that CCR4 can aggravate hepatocellular carcinoma malignancy and facilitate hepatocellular carcinoma cell metastasis via activating ERK/AKT/MMP2 pathway and CCR4 can promote colorectal cancer metastasis via activating ERK/NF-κB/MMP13 pathway." (PMID 39473097, 2025). "This seems to be supported by the fact that the matrix-metalloproteinase 13 (MMP13) is induced by CCR4 in an ERK/NFκB-dependent manner, facilitating invasiveness or migration of colorectal cancer cells through CCR4/CCL17-mediated Rho-kinase signaling." (PMID 30053879, 2018). "We evaluated Mmp13 gene expression in murine and human colorectal cancer cell lines and found that Mmp13 is expressed by the MC38 (murine) and HCT116 (human) colorectal cancer cell lines." (PMID 25880591, 2015). "ANGTL4, MMP13 and STC1 secretion by CAFs promotes metastasis of colorectal cancer." (PMID 37254126, 2023). "Previous studies have shown that the migration of colorectal cancer cells would be attenuated with downregulating MMP-3, and knockdown either MMP-3 or MMP-13 could repress the invasion and migration of anaplastic thyroid carcinoma cells." (PMID 32711573, 2020). "In the present study, we demonstrated that NF-κB but not β-catenin or Runx2, modulated the CCR4-mediated MMP13 activity in colorectal cancer cells, suggesting a crucial function of NF-κB in regulating invasiveness of tumor cells." (PMID 27356745, 2016). "MMP13 is involved in the breakdown of extracellular matrix in normal physiological processes and disease processes, they play a vital role in the prognosis of various cancers such as gastric cancer, colorectal cancer, and oral squamous cell carcinoma." (PMID 33352742, 2020).
prostate carcinoma (25 papers, 2008 to 2025). A carcinoma that arises from epithelial cells of the prostate gland. "We also determined if polymorphisms in several Zn-dependent genes (MT2A, MMP-1, MMP-2, MMP-7, MMP-13) contributed to prostate cancer risk." (PMID 30036379, 2018). "In this study we sought to analyze to what extent variations in serum Zn level and polymorphisms in MT2A, MMP-1, MMP-2, MMP-7 and MMP-13 are related to prostate cancer among Polish men." (PMID 30036379, 2018). "Cluster C2, associated with primary prostate cancer, expressed genes like MMP13 and POTEC." (PMID 40165961, 2025). "However, this same analysis also showed that expressions of MMP-13, as well as clustering for score values, were also independent factors associated with biochemical recurrence in patients with prostate cancer." (PMID 20160732, 2010). "Likewise, it is of note that the expression of MMP -13 (collagenase-3), which has been associated with the microinvasive component of "in situ" carcinomas, has been found to be up-regulated by androgens in prostate cancer derived the cell line LNCaP." (PMID 18507821, 2008). "The binding of Small leucine zipper protein (sLZIP) to MMP-13 promoter increased MMP-13 expression in prostate cancer cells." (PMID 35805035, 2022). "Another mechanism of melatonin was inhibiting of matrix metallopeptidase 13 (MMP-13) in prostate cancer cells in both in vitro and in vivo." (PMID 33923028, 2021). "MMP13 has an important role in bone remodeling, and in bone cancer and cancers that frequently metastasize to bone, such as breast and prostate cancer and multiple myeloma." (PMID 22253746, 2012). "These inhibitory effects of Cmpd-1 (MMP13-selective inhibitor) are consistent with the effects of several broader-spectrum MMP inhibitors on osteolysis associated with breast and prostate carcinoma cells." (PMID 22253746, 2012). "It has also been showed that plasma concentrations of MMP-13 were high in patients with metastasis of prostate cancer, and in these patients decreased markedly after the therapy began." (PMID 20160732, 2010). "The MMP-13 has been detected to be expressed by different prostate cancer cell lines, prostate cancer tissue and BPH." (PMID 20160732, 2010). "Interestingly, MMP2, MMP9 and MMP13 levels were increased in sEVs derived from hypoxic prostate cancer cells and hypoxic nasopharyngeal carcinoma cells and exosomal MMP13 has been shown to enhance migration and invasion of recipient cells in vitro and in vivo." (PMID 32709110, 2020). "In this study, we identified several genes including the cytokines Il-6, Tgfb2, Cxcl1, and Ctgf, metallopeptidases Mmp13, Adamts1, Adamts4, and Adamts5, and transcription factors Junb, Fos, Stat3 and Cebpb that were up-regulated in osteoblasts as a result of prostate cancer–osteoblast interactions." (PMID 27600237, 2015). "In addition, recent report indicated that androgen acts to stimulate the expression level of MMP-13 by LNCaP prostate cancer cell line." (PMID 20160732, 2010). "Then using SCID mice xenografted with PC-3 cells, they demonstrated that melatonin markedly inhibited MMP-13 expression in prostate tumor specimens and suppressed metastasis to distant organs, further exemplifying in vivo the anti-metastatic effects of melatonin on prostate cancer." (PMID 37191417, 2023). "They thus concluded that melatonin exerts anti-metastatic effects on prostate cancer via MT1 mediated inhibition of the PLC and p38 pathways, resulting in the inactivation of c-Jun with ultimate suppression of MMP-13." (PMID 37191417, 2023). "Prostate-cancer-cell-derived exosomal miR-139-5p and miR-21-5p remodeled ECM by promoting MMP-2 and MMP-13 expression in stromal cells, thereby contributing to PMN formation and distant metastasis of prostate cancer." (PMID 37046819, 2023). "In contrast, in high NLRP3-expressed cancer cells, such as prostate cancer cell line PC3, the secretion of VEGF and MMP-13 was higher compared to MCF-7 cells." (PMID 36902278, 2023).
prostate carcinoma (continued). "In contrast, CAV2 induces various epithelium-related molecules, including Vimentin, N-Cadherin, E-Cadherin, MMP13, and MYCL, which play important roles in prostate cancer cell motility." (PMID 35517414, 2022). "FOXO1 interacts with RUNX2 in vitro and in prostate cancer cells, and inhibits RUNX2 transcriptional activity on the OP, IL8, VEGF and MMP13 genes." (PMID 26204939, 2015). "This tumor-suppressive role has been suggested to be due to different pathways, including matrix metallopeptidase 9 (MMP-9) and matrix metallopeptidase 13 (MMP-13) down-regulation in lung mucoepidermoid carcinoma, as well as VEGF and MMP-9 downregulation in pancreatic and prostate cancers." (PMID 34439295, 2021). "In prostate cancer cells, stable expression of constitutively activated AKT (myr-AKT) induces the expression of RUNX2 mRNA and its target genes, such as PIP, PGC, MMP9 and MMP13." (PMID 26204939, 2015). "Likewise, our data led us to consider that MMP-13 and/or MMP-11 may be optimal therapeutic targets for inhibition in prostate carcinoma." (PMID 20160732, 2010).
colon carcinoma (21 papers, 2012 to 2025). "In the present study we analyzed whether polymorphisms rs28366003 in MT2A, rs1799750 in MMP-1, rs243865 in MMP-2, rs11568818 in MMP-7 and rs2252070 in MMP-13 genes are associated with the risk of breast, lung or colon cancer among polish subjects." (PMID 32765800, 2020). "The upregulation of ERK/NF-κB signalling enhanced the binding of NF-κB to Inhibitor of growth 2 (ING2) promoter, leading to the activation of ING2, which subsequently increased MMP-13 expression in colon cancer." (PMID 35805035, 2022). "The discovery that the inhibition of MMP-13 expression in MC38 colon cancer cells decreased the number of tumour cells extravasated from the hepatic vasculature in an experimental metastasis model is in line with this possibility." (PMID 35805035, 2022). "According to research, the CXCL13/CXCR5 axis promotes colon cancer incidence, progression, and metastasis by secreting MMP13 and activating the PI3K/AKT pathway." (PMID 34922542, 2021). "CXCL13 mediates distal metastasis of colon cancer by increasing the secretion of MMP13 and the activation of the PI3K/Akt pathway." (PMID 34947813, 2021). "Other markers of Paneth cells, such as secretory phospholipase A2 (PLA2G2A), MMP10 and MMP13, were also up-regulated, confirming that these cells are a cellular component of colon tumors, which is in agreement with previous reports." (PMID 26517809, 2015). "Our results indicate that both the MC38 murine colon cancer line and the HCT116 colon cancer cells express MMP13." (PMID 25880591, 2015). "During western blot of MMP13 in various colon cancer cell lines, active forms of MMP13 could be seen in all three (HCT116, RKO, CT-26) cell lines along with DCLK1-S while FoxD3 levels were minimally detected." (PMID 40839695, 2025). "In our analysis we did not observe correlation of rs2252070 in MMP-13 with breast, lung or colon cancer risk." (PMID 32765800, 2020). "To predict whether miRNAs target Mmp3, Mmp10, and/or Mmp13 in murine colon cancer cells, we first utilized the bioinformatics algorithms TargetScan, miRWalk, microRNA.org, and RNA22." (PMID 25742789, 2015). "In the case of CAC-associated MMPs (Mmp7, Mmp13) revealed in this study, focal high expression of Mmp7 was previously observed in CAC-related dysplastic lesions and its overexpression was associated with tumor growth, metastasis, and worse overall survival in patients with colon cancer." (PMID 36901742, 2023). "By utilizing RKO colon cancer cell line, we discovered that in response to PMA, a significant increase in MMP13 enzymatic activity was recorded with a dose-dependent decrease in response to MMP13 inhibitor WAY-170523 (Cat.# 2633, TOCRIS Biosciences)." (PMID 40839695, 2025). "Combining the expression trends of these genes in colon cancer and after aspirin treatment, we found that aspirin further upregulated NOX4, CXCL8, CXCL5, LIF, GDF15, and MMP13, while stimulated inhibition of IL2, NCF1, and PTGS1." (PMID 41425852, 2025). "This study reports that galectin-3 secretion by human colon cancer cells induces cancer cell secretion, in an autocrine/paracrine manner, of a number of proteases including cathepsin-B, MMP-1 and MMP-13." (PMID 37055381, 2023). "We found that the expression levels of some genes enriched in IL-11+ fibroblasts, including Wnt5a, Mmp13, Timp1, Il1rl1, Cxcl5, Saa3, Inhiba, Ascl4, and Tnfrsf11b, were elevated in mouse AOM/DSS-induced colon tumor tissues." (PMID 33863879, 2021). "Five SNPs, rs1799750 in MMP-1, rs243865 in MMP-2, rs11568818 in MMP-7, rs2252070 in MMP-13 and rs28366003 in MT2A has been studied in various cancers including breast, lung and colon cancer, but results were ambiguous." (PMID 32765800, 2020). "In a systematic analysis of MMP gene transcription, we identified the same three MMP genes [MMP1 (functional human homologue of mouse MMP13), MMP7 and MMP10] as target genes for acetylcholine-M3R activation in human colon cancer cell lines." (PMID 23617763, 2013).
colon carcinoma (continued). "The effect of IL-1β and IP6 on the expression of mRNA of MMP-1, MMP-2, MMP-3, MMP-9, MMP-10, and MMP-13 and that of their tissue inhibitors TIMP-1 and TIMP-2 in colon cancer cells using real-time QRT-PCR assay was determined." (PMID 22415590, 2012). "Matrix metalloprotein (MMP13) by degrading extracellular matrix (ECM) stimulates the release of VEGF from ECM and thereby promoting angiogenesis and metastasis in skin squamous cell carcinoma and colitis induced colon cancer." (PMID 34924998, 2021). "In colorectal or colon cancer, the CXCL13/CXCR5 axis mediates the pathogenesis, development, and distal metastasis of tumor cells through upregulating the expression and secretion of MMP13, as well as activating the PI3K/Akt pathway." (PMID 34947813, 2021). "The aim of this study was to investigate association of polymorphisms rs1799750 in MMP-1, rs243865 in MMP-2, rs11568818 in MMP-7, rs2252070 in MMP-13 and rs28366003 in MT2A, together with serum Zn level, with occurrence of breast, lung and colon cancer in Poland." (PMID 32765800, 2020). "We thus further analyzed the data from TCGA and showed that HPSE is positively correlated with the expression of MMP1 in colon cancer (r = 0.3476, p < 0.0001) and rectal cancer (r = 0.3428, p < 0.0001), but not MMP7, MMP10, and MMP13." (PMID 31001480, 2019). "Subsequently, wildtype and Mmp13−/− mice with and without steatosis were inoculated with 5 × 105 syngeneic MC38 colon cancer cells through the intrasplenic/portal route to generate experimental liver metastases." (PMID 25880591, 2015). "Colon cancer patients with upregulated NOX4, CXCL8, CXCL5, GDF15, or MMP13 may not benefit from aspirin chemoprophylaxis." (PMID 41425852, 2025).